CNTF (ciliary neurotrophic factor)
Diseases named in the same sentence as CNTF in open-access papers (continued):
Sharing a sentence is not in itself a finding about the gene and the disease.
multiple sclerosis (9 papers, 2012 to 2025). A progressive autoimmune disorder affecting the central nervous system resulting in demyelination. "CNTF, an important promyelinating factor, inhibited inflammatory pathology in experimental allergic encephalomyelitis (EAE), a mouse model of multiple sclerosis and astrocyte-derived CNTF protected oligodendrocytes from TNFα insult." (PMID 40004040, 2025). "Further investigations are necessary to find out the molecular and cellular mechanisms how HO-CO pathway improves clinical outcome in EAE model and multiple sclerosis by demonstrating the role of CO in CNTF-mediated CNS regeneration." (PMID 32218342, 2020). "Recently, it was shown that cortical neurons up-regulate a CNTF-mediated neuroprotective signalling pathway in response to chronic insults or stress in the pathogenesis of multiple sclerosis." (PMID 23236355, 2012). "CNTF has also been shown to promote survival and proliferation of oligodendrocyte precursor cells and protect the integrity of myelin sheaths in mouse model of multiple sclerosis." (PMID 36187291, 2022). "Neurotrophic factors such as CNTF may promote new myelin synthesis, consequently resulting in functional recovery in multiple sclerosis." (PMID 32218342, 2020). "In vivo, astrocytes derived from mice infected with the mouse hepatitis virus, a model for multiple sclerosis (MS), secrete high levels of CNTF during the remyelination phase while CNTF injection in the spinal cord upregulates the transcripts encoding FGF2, a potent OPC mitogen." (PMID 32317939, 2020). "With a smaller molecular weight and improved penetration into the brain parenchyma, Reg-2 may be a useful substitute for CNTF therapy in EAE and multiple sclerosis (MS)." (PMID 27242448, 2016).
Parkinson disease (8 papers, 2011 to 2025). A progressive degenerative disorder of the central nervous system characterized by loss of dopamine producing neurons in the substantia nigra and the presence of Lewy bodies in the substantia nigra and locus coeruleus. "Additionally, given that TBI is a potential risk factor for Parkinson’s disease, the protective role of CNTF could be significant in preventing the development of TBI consequences." (PMID 40353060, 2025). "CNTF effectively prevents the spontaneous degeneration of dopamine neurons and promotes behavioral recovery in Parkinson’s disease animal models through its action on CNTF receptor α (CNTFRα) expressed in substantia nigra dopamine neurons." (PMID 40353060, 2025). "Expression of CNTF and CNTFRα can increase in the brain following injury; however, the levels of CNTF are reduced in dopaminergic neurons in the substantia nigra (SN) of Parkinson’s disease (PD) patients and treatment with recombinant human CNTF preventes the degeneration of dopaminergic neurons." (PMID 25799580, 2015). "In patients with Parkinson's Disease, SVZ proliferation is markedly reduced, a side effect of loss of dopaminergic innervations related to the stimulatory activity of dopamine on EGF and CNTF secretion by SVZ NSCs." (PMID 22394166, 2012). "TRPV1 activation in the substantia nigra astrocytes is shown to produce ciliary neurotrophic factor (CNTF), which prevents the active degeneration of nigral dopaminergic neurons in rat models of Parkinson’s disease." (PMID 33613196, 2020). "Some of the neurotrophic effects of dopaminergic innervations are related to CNTF release, thus providing a mechanistic explanation for reduced SVZ cell proliferation in Parkinson Disease." (PMID 22394166, 2012).
Cachexia (7 papers, 2010 to 2025). Severe weight loss, wasting of muscle, loss of appetite, and general debility related to a chronic disease. "Haptoglobin protein levels are increased in a ciliary neurotrophic factor induced cachexia rat model and cachexia associated with congestive heart failure in human patients." (PMID 38022578, 2023). "IL-6 family cytokines other than LIF, which include IL-6, IL-11, and CNTF, were also reported as cachexia-inducing factors." (PMID 30410674, 2018). "On the other hand, when present systemically, ciliary neurotrophic factor (CNTF) is involved in the induction of cachexia, induces the catabolism of stored fat, skeletal muscle protein, and liver glycogen, and decreases the circulating concentrations of several intermediary metabolites." (PMID 40430444, 2025). "It has been well-documented that a wide variety of cytokines can induce cachexia after prolonged production via multiple mechanisms, and these cytokines include TNF-α, IL-6, leukemia inhibitory factor (LIF), ciliary neurotrophic factor (CNTF) and interferon-γ (IFN-γ)." (PMID 26064446, 2015).
Cognitive impairment (7 papers, 2017 to 2025). Abnormal cognition is characterized by deficits in thinking, reasoning, or remembering. "This study aimed at investigating the association of retinal abnormalities with serum CNTF level and other cognitive impairments in schizophrenia patients." (PMID 32676219, 2020). "T-tests and analysis of covariance were used to compare the variables between the patient and control groups, while multiple linear regression analysis was performed to determine the associations of RNFL thickness, CNTF and cognitive impairments." (PMID 32676219, 2020). "It was hypothesized that schizophrenia patients may show reduced RNFL thickness and that attenuated thickness may possibly be linked to lower levels of CNTF and cognitive impairments in schizophrenia." (PMID 32676219, 2020). "Recently, the association between the CNTF level in cerebrospinal fluid and AD progression has been found: a higher level of CNTF is related to a slower rate of cognitive impairment." (PMID 41562905, 2025). "CNTF is decreased in Schizophrenia, and it was significantly decreased as the severity of cognitive impairment increased." (PMID 39588547, 2024). "This study aimed at investigating retinal abnormalities and establishing their correlation with serum CNTF and cognitive impairments in schizophrenic Chinese patients." (PMID 32676219, 2020). "We observed that the CCH process-induced cognitive impairment decreased CNTF/CNTFRα/JAK2/STAT3 signaling, and induced irreversible neuronal death in the hippocampus." (PMID 33519417, 2020). "BDNF is more effective than CNTF in ameliorating cognitive impairment." (PMID 40380033, 2025). "In addition, CNTF rescues cognitive impairment in a dose-dependent manner, so bioavailability is essential for achieving cognitive repair." (PMID 39588547, 2024). "The decreased level of CNTF might contribute to a therapeutic intervention to prevent or reverse retinal dysfunction that might improve or prevent cognitive impairment in SSD." (PMID 39588547, 2024). "The neuroprotective effects of D3NB may be related to the regulation of CNTF signaling, which will ultimately improve cognitive impairment." (PMID 33519417, 2020). "Unlike previous scarce data and negative correlation, we also found increased levels of ciliary neurotrophic factor (CNTF) in plasma in several redescriptions describing subjects with high level of cognitive impairment, together with decreased levels of leptin." (PMID 29088293, 2017). "Compared to other neurotrophic factors, such as ciliary neurotrophic factor (CNTF), which improves synaptic plasticity and cognitive impairment in animals, it has severe adverse outcomes." (PMID 40380033, 2025). "The suggested biomarkers are CNTF and ADAM10, which have been clinically investigated in many retinal and cognitive disorders, creating a new pharmacological research venue for enhancing cognitive performance in SSD and ASD." (PMID 39588547, 2024). "5- Animal studies have reported the effectiveness of CNTF and ADAM10 in cognitive impairment." (PMID 39588547, 2024). "However, associations among CNTF, RNFL and cognitive impairments in schizophrenia are not yet clear." (PMID 32676219, 2020).
Hyperglycemia (7 papers, 2013 to 2023). An increased concentration of glucose in the blood. "They showed that ciliary neurotrophic factor (CNTF), a key neuropoietic cytokine, regulates the imbalance between neurogenesis and gliogenesis caused by hyperglycemia." (PMID 36509429, 2023). "Interestingly, transient administration of epidermal growth factor (EGF) and ciliary neurotrophic factor (CNTF) to adult mice with chronic hyperglycemia efficiently stimulates the conversion of terminally differentiated acinar cells to beta cells." (PMID 29227863, 2017).
neuroblastoma (7 papers, 2007 to 2025). Neuroblastoma (NB) is the most common solid, extracranial childhood tumor. "Low concentrations of MeHg enhance ciliary neurotrophic factor (CNTF)-evoked STAT3 phosphorylation in human neuroblastoma SH-SY5Y and mouse cortical neural progenitor cells (NPCs)." (PMID 40802001, 2025). "A role for ciliary neurotrophic factor (CNTF) in MMP modulation has been demonstrated in murine neuroblastoma cell models, where CNTF downregulated MMP-2, thus potentially to affecting invasive behaviour." (PMID 35794391, 2022). "Although we do not currently have a justification for why SH-CDKL5-KO cells are less responsive to P021 than primary neurons, we might hypothesize that neuroblastoma cells have lower CNTF receptor expression levels, and consequently a reduced responsiveness to the CNTF signaling." (PMID 39592934, 2024). "It is also very different from a study in human neuroblastoma cells which suggested that treatment with ciliary neurotrophic factor or a phorbol ester could induce a proteasome-dependent degradation of STAT3 which could be inhibited by MG132 and in which no discrete cleavage products were reported." (PMID 17295906, 2007).
breast carcinoma (5 papers, 2016 to 2024). "For example, miR-1290 upregulates ciliary neurotrophic factor (CNTF) expression by decreasing FOXA2 expression in astrocytes, promoting breast cancer cell growth and brain metastasis progression." (PMID 38605023, 2024). "Since STAT3 can be activated by a variety of cytokines, including IL-11, CNTF, LIF and G-CSF, in breast cancer, it is crucial to identify those tumors that depend on IL-6." (PMID 27602583, 2016).
depression (5 papers, 2020 to 2024). "CNTF levels increased in major depressive disorder, and CNTF was seen as a factor related to mental disease." (PMID 32894097, 2020). "Dysregulation of NTFs, particularly brain-derived neurotrophic factor (BDNF), ciliary neurotrophic factor (CNTF), glial cell line-derived neurotrophic factor (GDNF), and nerve growth factor (NGF), has been implicated in various cerebral disorders, including epilepsy and depression." (PMID 39474368, 2024).
epilepsy (5 papers, 2014 to 2024). A brain disorder characterized by episodes of abnormally increased neuronal discharge resulting in transient episodes of sensory or motor neurological dysfunction, or psychic dysfunction. "We showed BDNF decrease both in BS and LF of epilepsy patients, while, on the contrary, CNTF in these media was increased." (PMID 38069144, 2023). "Top upstream terms and network from the IPA analysis were HTT, NR4A1, CNTF, epilepsy, dyskinesia, synaptic depression, the organization of cells, and catalepsy." (PMID 36289639, 2022). "BDNF and CNTF levels did not depend on the etiology of epilepsy, while GDNF level was higher in two PWE subgroups as compared with the “trauma” subgroup." (PMID 36142325, 2022).
Huntington disease (5 papers, 2010 to 2024). Huntington disease (HD) is a rare neurodegenerative disorder of the central nervous system characterized by unwanted choreatic movements, behavioral and psychiatric disturbances and dementia. "CNTF is also neuroprotective in various models of acute neuronal death and neurodegenerative diseases, and it has been proposed as a neuroprotective agent for Huntington's disease (HD)." (PMID 20062544, 2010). "CCL5 treatment also influences development-related signaling, such as CNTF, VEGF, GNRH, and Huntington’s disease-related signaling molecules." (PMID 39285280, 2024). "Interestingly, CCL5 treatment also enhanced neuron development-related signaling, such as CNTF, VEGF, Huntington’s disease, and Reelin." (PMID 39285280, 2024).
motor neuron disease (5 papers, 2009 to 2023). "Mice and humans with mutations of CNTF display a progressive loss of motor neurons, and may have a higher risk of developing more severe motor neuron disease." (PMID 23472198, 2013). "Exogenous treatment with CNTF dramatically reduces degeneration in progressive motor neuropathy mice and co-treatment of the wobbler mouse model of motor neuron disease with CNTF and BDNF completely arrests disease progression for 1 month." (PMID 37692101, 2023). "Subcutaneous injections of CNTF, which was effective in the mutant mice models of motor neuron disease pmn/pmn and wobbler, did not affect the progression of disease in humans, but caused minor adverse side effects." (PMID 24616665, 2014). "Supporting this idea is a recent study whereby CNTF treatment in mice with motor neuron disease was shown to activate a pathway leading to microtubule stabilization, allowing axon elongation and maintenance." (PMID 25177267, 2014). "Our results provide new data and new insights into possible complications of utilizing CNTF as a therapeutic treatment for motor neuron diseases." (PMID 19267906, 2009). "CNTF was the first neurotrophic factor found to improve developing motor neuron survival after exogenous administration in both tissue culture and animal models, raising the possibility that it could be used as a potential treatment for motor neuron disorders." (PMID 37692101, 2023).
retinal disease (5 papers, 2011 to 2020). "The loss of neurotrophic properties of CNTF is correlated with retinal diseases in several animal models." (PMID 33173100, 2020). "Virtually every retinal disease is associated with ‘activation’ of Müller cells and reactive gliosis; it is possible that CNTF might be one of the endogenous inducers." (PMID 21637858, 2011). "The cytokine CNTF is of great interest as the protein’s neuroprotective effects on various retinal neurons have been demonstrated in numerous retinal disease models, subsequently ushering clinical evaluation in treating various retinal conditions in humans." (PMID 32629980, 2020). "Intraocular administration of CNTF has been found to attenuate photoreceptor degeneration and preserve retinal functions in animal research models of inherited or induced retinal disease." (PMID 32676219, 2020). "CNTF is the most effective of all factors tested for the ability to protect photoreceptors in a large variety of retinal diseases." (PMID 23209820, 2012). "Although the mechanisms and mediators of the biological effects of CNTF are still not fully resolved, its supportive and neuroprotective actions against retinal damage and degeneration have been demonstrated in various animal models of retinal disease." (PMID 32629980, 2020).
sarcopenia (5 papers, 2005 to 2024). Progressive decline in muscle mass due to aging which results in decreased functional capacity of muscles. "The observation of strength differences by CNTF genotype and the known role of CNTF on nerve development suggest that genetic differences are likely to impact on neuromuscular organization by altering muscle, nerve or both and may impact on the development of sarcopenia." (PMID 16181490, 2005). "On the other hand, genetic factors reported as sarcopenia biomarkers have also been identified such as angiotensin I-converting enzyme I (ACE), myostatin (MSTN), alpha actinin 3 (ACTN3), ciliary neurotrophic factor (CNTF), vitamin D receptor (VDR), insulin-like growth factor 1 (IGF1), and IL-6." (PMID 39194921, 2024).
Anorexia (4 papers, 2012 to 2017). Lack of desire to eat (loss of appetite). "Initially, it was proposed that activation of mTOR signaling in the hypothalamus promoted anorexia; in fact it was demonstrated that short-term central administration of anorectic factors, such as leucine, leptin, CNTF, α-lipoic acid or BMP7 increase hypothalamic mTOR signaling." (PMID 23056530, 2012). "However, in the hypothalamus the exact neurons activated by CNTF to induce anorexia and whether appetite-regulating neuropeptide gene expression is altered within CNTFR-expressing hypothalamic neurons remain to be determined." (PMID 23626705, 2013). "However, other than these two classical neuropeptide systems, we found that CNTF, at a dose that induced anorexia, activated hypothalamic ARC, LH, PVN, DMH and PeV (regions that widely express CNTFRs along with several neuropeptides involved in energy metabolism)." (PMID 23626705, 2013).
Anxiety (4 papers, 2015 to 2024). Intense feelings of nervousness, tension, or panic often arise in response to interpersonal stresses. "Considering that dopaminergic mechanisms underlie catalepsy and anxiety, and that CNTF has trophic effects for the dopaminergic neurons of the substantia nigra, we can speculate that P021, by affecting dopaminergic signaling, may selectively improve these defective behaviors." (PMID 39592934, 2024).
experimental autoimmune encephalomyelitis (4 papers, 2012 to 2023). An autoimmune demyelinating disease of the central nervous system that is produced experimentally in animals by the injection of homogenized brain or spinal cord in Freund's adjuvant. "CNTF is a neurotrophic factor that promotes remyelination by grafted or endogenous oligodendrocyte precursor cells after spinal cord injury and decreases myelin loss as well as the severity of functional loss after experimental autoimmune encephalomyelitis." (PMID 36930811, 2023). "In the murine experimental autoimmune encephalomyelitis (EAE) model, antagonism of LIF and genetic deletion of CNTF worsen disease." (PMID 23077604, 2012). "Importantly, the therapeutic administration of both CNTF and LIF has been shown to improve neurological outcome in the murine experimental autoimmune encephalomyelitis (EAE)." (PMID 23077604, 2012).
glioma (4 papers, 2013 to 2018). A benign or malignant brain and spinal cord tumor that arises from glial cells (astrocytes, oligodendrocytes, ependymal cells). "Our study demonstrated that hypomethylation leading to CNTFRα up-regulation, together with autocrine expression of CNTF, was involved in glioma growth regulation." (PMID 28765641, 2017). "CNTFRα and CNTF expression were profiled in three primary glioma cells and five established cell lines." (PMID 28765641, 2017). "The objective of the present study was to investigate the role of CNTF/CNTFRα and its regulation in gliomas." (PMID 28765641, 2017). "In addition, the effects of exogenous CNTF on glioma growth and knockdown of CNTFRα by siRNA on tumor inhibition were investigated both in vivo and in vitro." (PMID 28765641, 2017). "In our study, methylation of CNTFRα and autocrine CNTF from glioma cells activated the PI3K/AKT pathway, which could promote LGG progression." (PMID 28765641, 2017). "Aberrant growth factors and receptors such as EGF/EGFR2, IGF/IGFR3, PDGF/PDGFR4, and CNTF/CNTFR5, become constantly active and contribute to glioma progression." (PMID 28765641, 2017). "Furthermore, the role of CNTFRα in glioma proliferation and apoptosis through the PI3K/AKT pathways was demonstrated by supplementation with exogenous CNTF in vitro and siRNA knockdown in vivo." (PMID 28765641, 2017). "C6 glioma cells reportedly do not express the CNTF alpha receptor but can respond to CNTF, possibly through the IL-6 receptor to activate JAK-STAT3 (Tyr-705) signaling as shown in BaF3 cells." (PMID 23693126, 2013). "However, CNTF and its receptor CNTFRα have not been well demonstrated in gliomas." (PMID 28765641, 2017).